IL10 (interleukin 10)
Diseases named in the same sentence as IL10 in open-access papers (continued):
Sharing a sentence is not in itself a finding about the gene and the disease.
tumor (continued). "In addition, mouse Maf positive regulates the expression of Il-10, the paradigmatic anti-inflammatory cytokine that contributes to establish an anti-inflammatory and immunosuppressive environment in the tumor stroma." (PMID 36380627, 2023). "It was also found that macrophages exposed to tumor culture supernatants secreting more IL-10 that may trigger a rise of the intratumoral forkhead/winged helix scurfy (FoxP3)+ Tregs population, which are associated with HCC aggressive." (PMID 36816959, 2023). "Additionally, IL-10-producing B cells with regulatory properties were detected within the tumor microenvironment of solid tumors such as breast and ovarian cancer, collectively referred to as B10 Bregs." (PMID 37868967, 2023). "In the tumor microenvironment, IL-10 has a pleiotropic effect." (PMID 38258051, 2023). "Moreover, given the double tumor-promoting and tumor-repressing IL-10 action, both blocking and systemic administration of IL-10 have been explored as potential strategies for cancer immunotherapy." (PMID 37359549, 2023). "Interestingly, PD-1 blockade results in the compensatory release of IL-10 through tumor-infiltrating myeloid dendritic cells." (PMID 37138873, 2023). "Furthermore, Cyp11b1‐deficient tumours had reduced expression of the immunoregulatory molecules CD274 (PD‐L1), CD152 (CTLA‐4) and IL‐10." (PMID 36861295, 2023). "Likewise, an increase in anti-inflammatory cytokines such as IL-4 and IL-10, which are decreased in tumor processes, would presumably occur." (PMID 37960292, 2023). "Besides suppressing anti-tumor immunity by releasing anti-inflammatory cytokines such as IL-10 and TGFβ, they can provide oxygen for tumor growth by regulating angiogenesis." (PMID 36817451, 2023). "The observed effect in tumor development has been explained by the production of IL-10 by Tregs." (PMID 37622111, 2023). "Notably, the presence of CAFs has been found to induce the transformation of macrophages into an IL10-mediated tumor-promoting M2 phenotype." (PMID 37880682, 2023). "Accordingly, IRF4 deficiency further favors the generation of MDSCs in the TME, and increases the expansion of M-MDSCs and the infiltration of PMN-MDSCs with a strong suppressive capacity, which inhibits the proliferation of CD8+ T cells through IL10 and ROS generation and promotes tumor growth." (PMID 36814912, 2023). "Additionally, Tregs produce immune regulatory cytokines, including TGFβ and IL-10, which further contribute to the suppression of anti-tumor immune responses." (PMID 37771596, 2023). "Furthermore, to better understand the IL-10 role in tumorigenesis and the associated immune responses, it is necessary to further study and investigate the mechanisms that regulate IL-10 signaling and expression in tumor sites." (PMID 37835437, 2023). "Furthermore, IL-10 absence enhanced the efficiency of DC-based immunotherapy decreased Treg and MDSC levels in the tumor microenvironment, and boosted Th1-type antitumor responses, indicating that IL-10 promotes tumor growth in CRC." (PMID 38096329, 2023). "Interestingly, IL-10 antagonists are currently being explore as anti-tumor immune therapy in combination with TLR agonists and other immunostimulatory treatments." (PMID 36635337, 2023). "Moreover, hypoxia and acidosis can negatively impact the secretion of cytokines such as IL-10 by TAMs, which can hinder the immune response and promote tumor survival." (PMID 38033495, 2023). "In addition, WGP promoted the increase of Th1-type cytokines IFN-γ and IL-2 and the decrease of Th2-type cytokines IL-4 and IL-10, which can induce the differentiation of T cells, further demonstrated its anti-tumor ability." (PMID 36713833, 2023). "Additionally, the immune-suppressive impact of the Tr1-produced cytokine IL10 likely results in a net pro-tumor effect of the cytotoxic Tr1 cells." (PMID 37654482, 2023).
tumor (continued). "However, exposure to anti-inflammatory stimuli in the tumour microenvironment (such as IL-4 and IL-10) induces a specific M2-like phenotype of macrophages that promotes tumour cell proliferation, invasion, angiogenesis, and metastatic spread." (PMID 36900335, 2023). "Interestingly, IL-10 was over-expressed by all three monocyte subpopulations from patients with MGMT-unmethylated tumor compared to MGMT-methylated tumor." (PMID 36768201, 2023). "IL-10 is well-known for its role in M2 macrophage differentiation and for its immunosuppressive effects, which may contribute to tumor growth and progression." (PMID 37628994, 2023). "Therefore, Tregs promote tumor development or progression and exhibit anti-tumor immune responses by secreting IL-10 and TGF-β." (PMID 36721212, 2023). "In fact, tumor cells transformed to express IL-10 are rejected in immunocompetent hosts and transplantable tumors injected into genetically transformed mice to express human IL-10 in myeloid cells were rejected, depending on the presence of CD8+ T cells in the host." (PMID 37629156, 2023). "Perhaps myeloid HIF-2α drives excessive IL-10 in a tumor suppressive mechanism such as this." (PMID 37124241, 2023). "However, in patients with advanced HCC, activation of PD-1 signaling in B cells promotes IL-10 production and inhibits effector T-cell-mediated antitumor immunity, leading to early recurrence after tumor resection." (PMID 37275909, 2023). "IL10 is known to drive macrophage polarization towards a pro-tumor regulatory M2-like phenotype while IFNγ is known to drive macrophage polarization towards a stimulatory anti-tumor M1-like phenotype." (PMID 37654482, 2023). "M2 TAMs promote tumorigenesis, stemness maintenance, HGOS metastatization and immunosuppression on the activity of tumor-infiltrating lymphocytes (TILs) by releasing immunosuppressive soluble factors as IL-10, TGF-β2 (transforming growth factor-β2) and CCL22 (chemokine (C-C motif) ligand 22)." (PMID 36614241, 2023). "Furthermore, Treg-secreted IL-10 and TGF-β can induce neutrophil polarization and conversion to tumor-associated neutrophils (TANs)." (PMID 38096229, 2023). "Furthermore, in HCC tissues, CTLA-4 contributes to tumor growth by promoting immunosuppression through the induction of Treg activity and the production of indoleamine-2,3-dioxygenase and IL-10 in DCs." (PMID 36769116, 2023). "Furthermore, FAT4 expression was associated with markers of tumor-associated macrophages, such as CCL2, CD68, and IL-10." (PMID 37735184, 2023). "In addition, 5-HT decreases the expression of DC co-stimulatory molecules and increases IL-10 levels, thereby reducing the ability of DCs to stimulate T-cells, suppress cellular immunity, and promote tumor cell evasion of immune cell killing." (PMID 37153586, 2023). "Thus, IL-10 increases tumor cell survival, proliferation, and metastasis by controlling antitumor immunity." (PMID 36678874, 2023). "Additionally, Ad5f35 transduced macrophages did not differentiate into M2 macrophages when stimulated with IL-4, IL-10, IL-13 or a tumor-conditioned medium." (PMID 37510993, 2023). "Moreover, MC38 cells overexpressing ORM1 enhanced the tumor immune microenvironment by promoting macrophage M2 polarization and elevating interleukin-10 (IL-10) expression." (PMID 37640741, 2023). "Moreover, many studies have suggested that B10 cells that produce IL-10 can inhibit the antitumor effect of T cells and promote tumor growth." (PMID 35725835, 2023). "IL-6 and IL-10 are a group of cytokines, which are inducing tumor invasion and angiogenesis." (PMID 36825088, 2023). "Similarly, in tumour microenvironment, IL‐10‐producing Breg with a unique PD1hiCD5hiCD24−/+CD27hi/+CD3dim phenotype also elicited immunosuppressive functions and led to tumour progression in hepatocellular carcinoma." (PMID 37670492, 2023).
tumor (continued). "In addition, PARP14i reduced the production of suppressive factors such as TGFβ and IL-10, possibly contributing to the reduction in regulatory T (Treg) cells we observed in PARP14i-treated tumours." (PMID 37752135, 2023). "Furthermore, IL-10 secretion by these Bregs was markedly elevated in tumor-bearing mice treated with FGK, but to significantly less magnitude in those treated with FGK plus GSK." (PMID 37291146, 2023). "For instance, regulatory B cells producing IL-10 may contribute to immunosuppression in the tumor microenvironment." (PMID 37696458, 2023). "Furthermore, myeloid cells possibly suppress anti-tumor responses by secretion of IL10 and interaction via CD80/CD86 with CTLA-4 on reactive CD8+ T cells." (PMID 36761972, 2023). "The role of IL-10 in suppressing anti-tumour immune responses is more established." (PMID 37454231, 2023). "Bifidobacterium can directly induce DC maturation and cytokine (IFNγ, TNFα, IL-10, IL-17) production, thus promoting anti-tumor immunity and anti-PD-L1 efficacy and almost inhibiting tumor progression after combination therapy with PD-L1 monoclonal antibody (mAb)." (PMID 37841431, 2023). "Additionally, some cytokines including TGF-β, IL-10 and IL-6 were described to facilitate tumor escape." (PMID 37340387, 2023). "Infiltrated immune cells shift their phenotypes from anti-tumor, also known as pro-inflammatory phenotypes, to pro-tumor phenotypes because tumor cells increase interleukins and chemokines such as IL-2, IL-4, IL-6, IL-7, IL-10, IL-12, and CXCL12 concentrations." (PMID 37533070, 2023). "Adaptive plasticity of IL-10+ and IL-35+ Treg cells cooperatively promotes tumor T cell exhaustion." (PMID 37182149, 2023). "Despite reducing tumor-promoting inflammation, IL-10 may play a role in the rejuvenation of exhausted tumor-resident T cells." (PMID 38003396, 2023). "IL-10 is an important factor that enables tumor cells to escape immune attack." (PMID 37965271, 2023). "IL-6, TGF-β, IL-10 and other pro-inflammatory factors secreted by tumor cells could promote chronic inflammation by stimulating MDSCs, macrophages, and neutrophils to further secret IL-6, TGF-β, IL-10." (PMID 37644468, 2023). "M2 macrophages are usually considered to be anti-inflammatory and pro-tumor, as they can secrete ornithine, interleukin-10 and other regulatory molecules that promote tissue repair and angiogenesis, as well as participate in immune suppression and tumor development." (PMID 38283752, 2023). "Alternatively, patients with LM who are non-responders may have genetic polymorphisms that influence the secretion of interleukin-10, an inhibitory cytokine that slows the generation of CD4 and CD8 effector T cells, which are able to kill tumor cells." (PMID 36900337, 2023). "This may be because the TME with high APOC1 expression affects the polarization of macrophages, causing macrophages to secrete substances such as IL10, which in turn causes pro-tumorigenic effects of macrophages on ESCA cells, leading to tumor development." (PMID 36969562, 2023). "Mechanistic studies reveal that Fe-CDs can selectively promote tumor cell apoptosis through regulating PARP/Caspase 3/Caspase 9/BAX proteins, and activate antitumoral macrophages by inhibiting the IL-10/Arg-1 axis, which contributed to the superior anti-tumor performance of Fe-CDs." (PMID 37978538, 2023). "On the other hand, MGL-mediated engagement of DCs with GalNAc-containing ligands can enhance DC cell activation and survival by activation of MAPK/ERK and NF-kappaB signalling, resulting in an increase of CD8+ T cell mediating anti-tumour response and secretion of IL-10 and TNF-α by DCs." (PMID 37612278, 2023). "A 2021 publication in Nature has identified B cell-derived GABA promotes monocyte differentiation into IL-10(+) macrophages and limits anti-tumor immunity by inhibiting CD8(+) T cell killer function, establishing a suppressive TIME via modulating macrophage differentiation." (PMID 37215113, 2023).
tumor (continued). "However, due to the variable biological activity of IL-10 in the tumor microenvironment, it is mandatory to conduct a careful clinical investigation to define the timing and method of anti-IL-10 agent administration." (PMID 37835437, 2023). "Tumor-induced regulatory DC subset inhibit immunity via CTLA-4-dependent IL-10 and IDO production." (PMID 36845131, 2023). "However, in the LY2 model, IL-10 was higher in lymph node cells stimulated with the IR tumor antigen compared to CD3/CD28 antibody stimulation." (PMID 37444444, 2023). "Furthermore, IL-6, IL-8, and IL-10 production by cells from the TME mediate pro-tumor functions of immune cells, such as neutrophils and macrophages." (PMID 37292196, 2023). "Some studies indicate that IL-10 promotes tumor growth and progression." (PMID 36771154, 2023). "The production of IL-10 by Tregs may be crucial for the survival and proliferation of tumor cells, as it regulates antitumor immunity." (PMID 37828948, 2023). "Moreover, M2-TAMs play a crucial role in tumour progression due to their influence on epithelial-mesenchymal transition (EMT) of the primary tumour by means of in-inflammatory cytokines and growth factors, such as IL-6, IL-10, and TGFβ." (PMID 36857852, 2023). "However, tumor-infiltrating B cells are also able to promote angiogenesis or secrete immunoregulatory cytokines, including TGFβ and IL-10, that suppress the anti-tumor immune response and its effector cells." (PMID 37266839, 2023). "IL-10 is secreted by tumor cells as a tumor infiltratory macrophage." (PMID 37298889, 2023). "We showed that C3a plays a crucial role in the tumor microenvironment and may influence the tumor’s fate by modulating the expression of cytokines (including IL-10, TGFβ1), chemokines, Cox-2, and HO-1, and upregulating the oxidative stress response." (PMID 37296948, 2023). "M2 microphages on the other hand typically aid cancer progression by secreting anti-inflammatory cytokines such as IL-10 to inhibit DC maturation and antigen presentation, and help T regulator (TReg) cell recruitment to the tumour microenvironment to exert immunosuppression." (PMID 37612278, 2023). "In addition, DEGs between the control and KD groups were highly enriched for inflammatory pathways, such as inflammatory response, tumor inflammation signature, and IL-10 anti-inflammatory signaling pathway." (PMID 38025532, 2023). "Recent studies have demonstrated that metastatic OS-cell-derived exosomes can induce the M2-type differentiation of macrophages largely through Tim-3 mediation and create an immunosuppressive tumor-promoting microenvironment through the production of cytokines, including IL-10, TGF-β, and VEGF." (PMID 36979391, 2023). "Furthermore, pDCs produce IL-10, which facilitates tumor immune escape by reducing the T-cell response and inducing regulatory T-cell hyperplasia." (PMID 37674204, 2023). "For example, it has been observed that dioscin induced macrophage M2-to-M1 phenotype transition in vitro and inhibited IL-10 secretion, and it may act as a new anti-tumor agent by down-regulating STAT3 and JNK signaling pathways in macrophages in vitro." (PMID 37816138, 2023). "In TME or TIME infiltrated B cells under the influence of IL-6, IL-1β, IL-12p35, and low oxygen (tumor-promoting molecules), which polarize to regulatory B cells (Bregs), producing TGF-β, granzyme B (GZMB), IL-10, and IL-35, which promote tumor growth and metastasis." (PMID 37275901, 2023). "In addition to promoting tumor cell migration and angiogenesis, M2 macrophages can induce the secretion and expression of cytokines such as IL-10 and M-CSF by releasing FGL2, thereby promoting the polarization of macrophages toward the M2 phenotype." (PMID 37359527, 2023). "Moreover, Il-10 has been shown to induce the polarization from M1 macrophages to the M2 phenotype while simultaneously promoting tumor growth, invasion, and angiogenesis." (PMID 38137547, 2023).
tumor (continued). "TGF-β causes immunosuppression by acting on macrophages, tilting their function to favor tumor growth, and promoting their ability to release other immunosuppressive cytokines, such as interleukin-10 (IL-10); it also inhibits DC function, curbs T cell responses and inhibits NK cells." (PMID 36937319, 2023). "It is also unclear that the IL-10 released can successfully limit adverse immune responses and may even facilitate tumor progression by suppressing anti-tumor macrophages within the TME." (PMID 37529036, 2023). "Moreover, we also observed an increase in expression of CD206, a marker of TAMs, and the production of IL-10 in tumor-CM-induced TAM-like THP-1 compared with M0-like THP-1 macrophages." (PMID 37567973, 2023). "Activated M2 macrophages produce small amounts of IL-12 and large amounts of IL-10, which suppress the inflammatory state of the body, attenuates the antineoplastic immune response, promote tumor angiogenesis, and accelerate tumorigenesis, development, and metastasis." (PMID 37153586, 2023). "Th2 cells produce IL-4 and IL-10 and favor tumor growth by inhibiting the host immune system." (PMID 37894300, 2023). "As IL-10 and TGFβ are associated with suppressive Treg cells and these cells expressed the highest levels of TGFβRII of the T cells in the TME, we next investigated the phenotype of Treg cells between the tumor types." (PMID 37552475, 2023). "However, the results showed that ENO1 inhibited IL-10 mRNA levels in the early stage of tumor-conditioned medium (TCM) incubation." (PMID 36614179, 2023). "α-PD-1 monoclonal antibodies reverse T cell exhaustion in cancer patients and restore anti-tumor potential of T cells Further upstream, blocking IL-10 inhibits upregulation of PD-L1 and α-IL-10 decreases frequency of PD1+ cells (preliminary data from our group DOI: 10.1101/2021.02.26.432955)." (PMID 36569952, 2022). "The 24-month overall survival probability in a cohort of patients with high gene expression versus low gene expression of listed chemokines in tumor specimens was 0.2 vs. 0.35 for IL-4, 0.2 vs. 0.35 for IL-10, 0.2 vs. 0.4 for CCL2, 0.2 vs. 0.57 for GM-CSF, and 0.15 vs. 0.23 for VEGF." (PMID 35884700, 2022). "IL-10 promotes tumor proliferation by inhibiting immune responses in various malignancies." (PMID 35884907, 2022). "In addition, B cells producing suppressive cytokines such as IL10, e.g., so-called regulatory B cells (Bregs), were also identified in the tumor microenvironment (TME) in certain tumor types and were demonstrated to dampen anti-tumor immunity." (PMID 36230721, 2022). "The long-term chronic inflammatory microenvironment, the secretion of immunosuppressive factors such as IL-10, abnormal autoimmune response, and the use of immunosuppressive drugs have led to frequent tumor-like symptoms and paraneoplastic syndromes in RA patients." (PMID 35663045, 2022). "Moreover, ICB also exerted an influence on DCs: in response to IFN-γ produced by T cells and NKs, tumor-infiltrating DCs expressed more co-stimulatory molecules and a higher IL-12/IL-10 ratio." (PMID 35326515, 2022). "In addition to arginase, various other soluble mediators expressed by immunosuppressive myeloid cells have been shown in human studies to contribute to tumor immunoevasion, such as IL-10, TGF-β1, IL-6, and inducible nitric oxide synthase (iNOS)." (PMID 35878391, 2022). "This therapy induces tumor-infiltrating plasmacytes that express IgA, IL-10 and PD-L1." (PMID 35651611, 2022). "In particular, NG + CSO upregulated the expression of IL-6 and IL-10 in the serum of tumor-bearing mice and significantly increased the spleen index, suggesting that the combination of the two via nanotechnology could enhance the antitumor immune effect." (PMID 36212483, 2022).